NSUN5 (NOP2/Sun RNA methyltransferase 5)
Diseases named in the same sentence as NSUN5 in open-access papers (continued):
Sharing a sentence is not in itself a finding about the gene and the disease.
chronic liver failure (1 paper, 2025). Liver failure that develops slowly and gradually for some time, possibly for years, often as the result of cirrhosis, or malnutrition. "Niujiao Dihuang Jiedu decoction has a significant therapeutic effect on acute-on-chronic liver failure, where it inhibited acute-on-chronic liver failure-related ferroptosis by promoting SLC7A11 m5C methylation, which is generated by binding to NSUN5." (PMID 41462962, 2025).
congenital heart disease (1 paper, 2021). A heart disease that is present at birth. "However, the function and mechanism of NSUN5 in congenital heart disease and heart development remain to be defined." (PMID 33968922, 2021).
congenital heart malformation (1 paper, 2021). A disease that has its basis in the disruption of heart development. "NSUN5, acting as a cytosine-5 RNA methyltransferase, a post-transcriptional modification, is located in the 7q11.23 locus and patients with this locus deletion have congenital heart malformation, including TOF." (PMID 33968922, 2021).
developmental delay (1 paper, 2021). "The results suggest that the wildtype mice would get phenotypic recovery with advance of development process, yet part of Nsun5 null mice still had OFT developmental delay." (PMID 33968922, 2021).
esophageal cancer (1 paper, 2025). A primary or metastatic malignant neoplasm involving the esophagus. "NSUN5 is significantly upregulated in esophageal cancer (ESCA) and has demonstrated good diagnostic potential." (PMID 41462962, 2025). "In esophageal cancer, NSUN5 is associated with METTL1 and positively regulates its expression, where NSUN5 directly binds to the METTL1 transcript, promoting its m5C modification in esophageal cancer cells." (PMID 41462962, 2025).
hypercalcaemia (1 paper, 2019). "NSUN5 is deleted in around 95% of WBS patients, who show clinical phenotypes including growth retardation, a dysmorphic face, behavioral and cognitive alterations, hypercalcaemia, as well as aortic and pulmonary stenosis." (PMID 31722427, 2019).
kidney papillary carcinoma (1 paper, 2025). "Finally, in kidney papillary carcinoma (KIRP), the signature included YTHDC2, IGF2BP2, DNMT3B, TRMT6, HNRNPC, and NSUN5." (PMID 40565233, 2025).
melanoma (1 paper, 2022). A malignant, usually aggressive tumor composed of atypical, neoplastic melanocytes. "In melanoma, the increased expression of NSUN5 is used to predict the sensitivity of melanoma cells to the pyrazopyrimidine derivative c-Src inhibitor 10a." (PMID 35562754, 2022).
neuroblastoma (1 paper, 2025). Neuroblastoma (NB) is the most common solid, extracranial childhood tumor. "We further explored the association between the NSUN5 gene rs1880948 A>G polymorphism and neuroblastoma susceptibility based on age, gender, origin sites, and clinical stages." (PMID 41536427, 2025). "We designed a case-control study of children from Jiangsu Province to determine the association between NSUN5 gene polymorphisms and neuroblastoma susceptibility in the Chinese population." (PMID 41536427, 2025). "Here, we performed a hospital-based case-control study using data from 402 neuroblastoma patients and 473 control subjects to evaluate the association between the NSUN5 gene (rs1880948 A>G) polymorphism and neuroblastoma risk in Chinese children." (PMID 41536427, 2025). "Stratification analysis for the association between NSUN5 rs1880948 A>G polymorphism and neuroblastoma susceptibility." (PMID 41536427, 2025). "Nevertheless, the relationship between NSUN5 polymorphisms and neuroblastoma susceptibility remains unclear, warranting further investigation to elucidate their role in neuroblastoma." (PMID 41536427, 2025). "We, therefore, focused on whether m5C modification gene NSUN5 polymorphisms have an impact on genetic susceptibility to neuroblastoma." (PMID 41536427, 2025). "This variant could affect transcription factor or microRNA binding and thereby influence NSUN5 expression, a mechanism also reported for other gene SNPs.However, the important role of NSUN5 gene polymorphisms in neuroblastoma is still unclear." (PMID 41536427, 2025). "NSUN5 rs1880948 A>G polymorphism and neuroblastoma risk in children from Jiangsu province." (PMID 41536427, 2025). "This study explores the potential association between the RNA modification gene NSUN5 polymorphism and susceptibility to neuroblastoma, which has not been previously reported." (PMID 41536427, 2025). "However, we did not detect a significant effect on neuroblastoma susceptibility for the NSUN5 rs1880948 A>G polymorphism." (PMID 41536427, 2025). "In summary, our study indicates that the selected NSUN5 rs1880948 A>G polymorphisms may not be associated with neuroblastoma susceptibility." (PMID 41536427, 2025).
preeclampsia (1 paper, 2025). Preeclampsia is a hypertensive disorder of pregnancy that is characterized by new-onset hypertension with proteinuria presenting after 20 weeks of gestation, and depending on mild or severe forms may initially present with severe headache, visual disturbances, and hyperreflexia. "The decidua tissue of women with severe gestational hypertension had significantly downregulated NSUN5 expression compared to the decidua tissue of normal pregnant women." (PMID 41462962, 2025). "NSUN5 mutations may alter decidualization through the L-11Rα–JAK2–STAT3–cyclin D3 pathway, affecting placental development and promoting the occurrence of preeclampsia." (PMID 41462962, 2025).
renal cell carcinoma (1 paper, 2025). "Furthermore, NOP2, NSUN2, and NSUN5 mRNA were significantly upregulated in renal cell carcinoma tissue, while NSUN4 mRNA was downregulated." (PMID 41462962, 2025).
tumor (33 papers, 2019 to 2026). "Recent studies have demonstrated that NSUN5 is aberrantly expressed in multiple cancer types, and its upregulation is often associated with advanced tumor stage, poor prognosis, and immune evasion." (PMID 41695396, 2026). "IHC staining confirmed elevated NSUN5 expression in HCC tumor tissues compared to adjacent tissues, often associated with poor patient prognosis." (PMID 39531371, 2025). "RECQL4, UTP6, CCNT1, and NSUN5 were enriched in the regulation process of cyclin dependent protein kinase activity, Cyclin D1 is one of the effectors of tumor gene Neu and Ras causing malignant transformation of cells in breast cancer." (PMID 39095659, 2024). "The knockdown of NSUN5 results in the loss of methylation at the C3782 position of 28S rRNA, leading to an overall decline in protein synthesis and tumor cell proliferation." (PMID 38182896, 2024). "Among the upregulated genes, Nsun5 (RNA methyltransferase 5) is known for its role in mRNA methylation and its association with tumor invasion and metastasis in humans." (PMID 39769404, 2024). "Gene Ontology and gene set variation analyses showed that NSUN5 was associated with tumor immunity in ccRCC." (PMID 37263638, 2023). "Epidemiologic study demonstrated that high expression of NSUN5 was associated with advanced tumor stages (III, IV), which possibly relate to its promotion of cell proliferation through regulating cell cycle in CRC." (PMID 36319976, 2022). "Finally, NSUN5 upregulation in CRC cells was associated with advanced tumor stages (III, IV) and induced cell cycle arrest in vitro." (PMID 41462962, 2025). "Among them, DNMT3b, DNMT1, ALYREF, TET2, NSUN2 and NSUN5 mutations imply that m5C may act abnormally in the tumour." (PMID 37408139, 2023). "Most important, and as it also occurs with the isocitrate dehydrogenase (IDH1) mutations, the presence of NSUN5 DNA methylation-associated silencing in human gliomagenesis identifies patients with good clinical outcome, which is an exceptional feature of people affected by this tumor type." (PMID 31428936, 2019). "NSUN5 can also mediate tumor microenvironmental regulation through RNA modifications, such as modulating macrophage polarization, enhancing antioxidative capacity, and facilitating immune escape." (PMID 41695396, 2026). "Mechanistically, NSUN5 modulates the m5C modification of rRNA or specific mRNAs, reshaping the cellular proteome and influencing tumor cell proliferation, migration, invasion, and stemness maintenance." (PMID 41695396, 2026). "Our analysis revealed a significant correlation between NSUN5 expression and multiple immune checkpoint molecules, suggesting a potential role for NSUN5 in modulating tumor immune evasion." (PMID 41555554, 2026). "To investigate the relationship between NSUN5 expression and the tumor immune microenvironment, we used the CIBERSORT algorithm to estimate the relative abundance of 22 immune cell types." (PMID 41555554, 2026). "NSUN3 and NSUN5 have begun to demonstrate their ability to regulate the tumor immune microenvironment, affecting macrophage polarization and T cell function, providing new targets for combined immunotherapy." (PMID 41256854, 2025). "In the present study, using multiple cellular and animal models, we found that knocking out NSUN5 in HCC substantially reduced tumor proliferation and suppressed metastatic potential." (PMID 39531371, 2025). "Following induction with DEN and CCL4, we observed significantly reduced tumor size and number in the livers of Nsun5‐KO mice compared to wild‐type mice, confirming the involvement of NSUN5 in HCC malignancy." (PMID 39531371, 2025). "In this study, clinicopathological analyses are conducted across multiple independent HCC cohorts and induced tumor formation in Nsun5‐knockout mice." (PMID 39531371, 2025).
tumor (continued). "First, using subcutaneous tumor formation in mice, we observed that NSUN5 overexpression increased HCC proliferation, an effect significantly attenuated by reducing WDR5 levels in HepG2‐ov‐NSUN5 cells." (PMID 39531371, 2025). "To further elucidate its role in HCC, we quantified NSUN5 expression in tumor tissues relative to adjacent tissues using quantitative reverse transcriptase polymerase chain reaction (qRT‐PCR) and western blotting assays." (PMID 39531371, 2025). "Subsequently, tumor formation experiments in nude mice revealed that NSUN5 KO significantly reduced SMAD3 and p‐SMAD3 levels in tumors, accompanied by an increase in E‐cadherin (an epithelial marker) and a decrease in vimentin (a mesenchymal marker)." (PMID 39531371, 2025). "NSUN5 is overexpressed in GC tissue, positively correlated with tumor staging, and negatively correlated with patient prognosis." (PMID 41462962, 2025). "In patients with HCC, NSUN5 exhibited significant upregulation in primary tumor tissues (n = 371) compared with normal liver tissues (n = 50)." (PMID 38182896, 2024). "In this study, we observed a remarkable upregulation of NSUN5 expression in both tumor tissues from patients with HCC, establishing a correlation with unfavorable clinical outcomes." (PMID 38182896, 2024). "Our experiments indicated that overexpressing ZBED3 reinstates the tumor-suppressive effects observed upon NSUN5 knockdown in Huh7 and Hep 3B cells." (PMID 38182896, 2024). "Taken together, these results indicate that elevated NSUN5 expression in patients with HCC plays a crucial role in tumor progression and holds promise as a prognostic marker." (PMID 38182896, 2024). "In this study, we found that NSUN5 expression is elevated in tumor tissues compared with normal liver tissues of patients with HCC." (PMID 38182896, 2024). "In gastric cancer, NSUN5 modulates ferritin heavy chain 1 and inhibits ferroptosis, ultimately enhancing tumor cell proliferation." (PMID 38182896, 2024). "Taken together, our results suggest that NSUN5 plays a protumorigenic role in GBM by enabling the enhanced protein synthesis requisite for tumor progression." (PMID 37057706, 2023). "The western blotting analysis further verified NSUN5 expression in the subcutaneous tumor tissues in vivo." (PMID 37263638, 2023). "The transwell invasion assays showed that after NSUN5 knockout and downregulation, the cell penetration capacity and invasiveness of the tumor cells decreased." (PMID 37263638, 2023). "A xenogeneic ccRCC mouse model was established to study the anti-tumor effects of knocking down NSUN5 on ccRCC cells in vivo." (PMID 37263638, 2023). "Among the differentially expressed genes present, DNMT1, NSUN2, NSUN4, and TET2 were highly expressed in LNM + tumor tissues while NSUN5 and NSUN7 expression was reduced." (PMID 37907576, 2023). "The ensuing question was how CRC tumor cells led to high expression of the m5C-modified regulators NSUN5 and YBX1 in immune cells of peripheral blood." (PMID 36211353, 2022). "NSUN2, NSUN5, NSUN6, DNMT3A, DNMT3B, ALYREF, and TET3 acted as tumor risk factors, and overexpression of these genes led to a poorer prognosis for ccRCC patients." (PMID 36661693, 2022). "In vitro co-culture experiments also demonstrated that CRC tumor cells promoted NSUN5 and YBX1 expression in immune cells, resulting in elevated m5C levels." (PMID 36211353, 2022). "Moreover, NSUN5 participates in tumor metabolic reprogramming, including glycolysis and lipid biosynthesis, as well as in cellular stress responses and resistance to chemotherapy and radiotherapy." (PMID 41695396, 2026).
tumor (continued). "In another set of samples, qRT‐PCR demonstrated significantly higher NSUN5 expression in tumor tissues than in normal tissues, indicating that high NSUN5 expression may hold clinical significance in HCC." (PMID 39531371, 2025). "Silencing NSUN5 enhanced tumor cell aging while inhibiting cell proliferation and migration." (PMID 41462962, 2025). "Moreover, 28S rRNA methyltransferase NSUN5 downregulates β-catenin by promoting CTNNB1 mRNA degradation, thereby enhancing the phagocytic activity of tumor-associated macrophages (TAMs)." (PMID 40370440, 2025). "Furthermore, analysis of HCC data from The Cancer Genome Atlas (TCGA) database revealed that NSUN5 is markedly upregulated in tumor tissues compared to adjacent tissues." (PMID 39531371, 2025). "In colorectal cancer, NSUN5 acts as a tumor promoter by regulating the cell cycle." (PMID 38182896, 2024). "Additionally, we found that the overexpression of ZBED3 counteracted the tumor-suppressing effect of NSUN5 knockdown and simultaneously reversed the inhibition of the Wnt/β-catenin signaling pathway." (PMID 38182896, 2024). "Conversely, NSUN5 overexpression significantly enhanced tumor cell proliferation." (PMID 38182896, 2024). "Overall, our findings prove that NSUN5 serves as a tumor-promoting gene in HCC." (PMID 38182896, 2024). "The researchers hypothesized that NSUN5 facilitates tumor growth by enhancing protein translation, although the precise molecular mechanisms remained elusive." (PMID 38182896, 2024). "In addition, ZBED3 overexpression almost completely reversed the tumor-suppressive effect induced by NSUN5 knockdown." (PMID 38182896, 2024). "Tumor migration decreased after the downregulation of NSUN5." (PMID 37263638, 2023). "Knockdown of NSUN5 inhibits tumor growth in vivo and in vitro." (PMID 36941538, 2023). "Interestingly, however, contradictory to our findings, they showed that NSUN5 plays a tumor suppressing role in GBM: NSUN5 overexpression decreases, whereas NSUN5 knockdown increases, cell proliferation in vitro and tumor formation and progression of GBM cells in vivo." (PMID 37057706, 2023). "Our results demonstrated that NSUN5 KO significantly decreased intracellular SMAD3 and p‐SMAD3 levels, reversing EMT in tumor cells and significantly reducing HCC invasion and metastasis both in vitro and in vivo." (PMID 39531371, 2025). "Expression overlays of six RNA modification genes selected by the LASSO Cox model (DNMT1, DNMT3A, HNRNPC, IGF2BP2, NSUN5, and ZC3H13) demonstrated variable distribution across the tumor microenvironment." (PMID 40565233, 2025). "A previous study revealed that elevated NSUN5 expression promotes both in vitro HCC cell proliferation and migration as well as in vivo HCC tumor growth." (PMID 38182896, 2024). "The PCR results showed that NSUN5 and HNRNPA2B1 expression was higher in tumor tissues than in normal tissues." (PMID 35571068, 2022). "Regulators with amplificated CNV tended to highly expressed in tumor samples (e.g., DNMT1, ALYREF, and NSUN5), and vice versa (e.g., NSUN7 and NSUN6)." (PMID 36389669, 2022). "NSUN5 and HNRNPA2B1 expressions were higher in tumor tissues than in normal tissues, consistent with our other findings." (PMID 35571068, 2022). "qRT-PCR results demonstrated elevated levels of NSUN5 and YBX1 in blood immune cells of CRC tumor-bearing mice." (PMID 36211353, 2022). "Current studies have identified the carcinogenic role of NSUN5 and YBX1 in CRC tumor cells, but their expression and function in the immune microenvironment remained unclear." (PMID 36211353, 2022). "The level of NSUN3 and NSUN6 was increased in tumor samples, whereas the level of ALYREF, NSUN5, and NSUN7 was decreased in tumor samples." (PMID 33365328, 2020). "Western blotting revealed higher NSUN5 expression in tumor tissues compared to corresponding nontumor tissues." (PMID 39531371, 2025).
tumor (continued). "However, knocking down WDR5 in NSUN5‐overexpressing HCC cells significantly reduced the number and size of metastatic lesions in the lungs, accompanied by decreased metastatic tumor volume in the lungs, as validated via IHC staining." (PMID 39531371, 2025). "As GBM is a highly heterogeneous tumor, it will be important to carry out additional analysis using GBM protein datasets as they become available in order to further investigate the correlation between NSUN5 at the protein level and GBM patient survival." (PMID 37057706, 2023). "The expression of ALKBH1 (p = 0.036), ALYREF (p < 0.001), NOP2 (p < 0.001), NSUN2 (p < 0.001), NSUN4 (p < 0.001), NSUN5 (p < 0.001), NSUN6 (p < 0.001), NSUN7 (p = 0.006), and YBX1(p < 0.001) were significantly upregulated in tumor tissues compared with the adjacent mucosa." (PMID 35281843, 2022). "In addition, the expressions of DKC1, NSUN5, FLNA and CSE1L were validated by qRT-PCR and IHC, and found that DKC1, CSE1L and NSUN5 were highly expressed and FLNA was underexpressed in CRC tumor tissues, consistent with the data in TCGA database." (PMID 36319976, 2022). "The findings reveal an upregulation of NSUN5 expression in tumor tissues; conversely, the absence of Nsun5 hinders the malignant progression of HCC, indicating that NSUN5 may serve as a significant oncogene in HCC." (PMID 39531371, 2025). "Moreover, five writers (NOP2, NSUN2, NSUN3, NSUN4 and NSUN5), one reader (ALYREF) and two erasers (TET2 and TET3) were consistently upregulated in UCB tumor tissues compared to adjacent normal tissues from TCGA cohort (fold change > 1.1, P-value <0.05, occurrence rate > 50%)." (PMID 36806253, 2023). "Besides, both univariate and multivariate Cox analyses revealed that the risk score could act as an independent prognostic factor in HNSCC, implying that NSUN5, DNMT1, and DNMT3A could be involved in tumor oncogenes and suppressors." (PMID 33912441, 2021).